BACH1 (BACH transcriptional regulator 1)
Diseases named in the same sentence as BACH1 in open-access papers (continued):
Sharing a sentence is not in itself a finding about the gene and the disease.
cancer (continued). "The transcription factor BACH1 regulates heme homeostasis and oxidative stress responses and promotes cancer metastasis upon aberrant accumulation." (PMID 38895309, 2024). "The activity of GATA‐family and MEF2C TF was upregulated in luminal cancer cells, while that of the ATF (BATF/MAFK/MAFF/BACH1) TF was upregulated in basal cancer cells." (PMID 38582099, 2024). "Hemin sensitizes TNBC to metformin by promoting the degradation of BACH1, making combined hemin-metformin treatment a potential therapeutic strategy for other cancer types, such as papillary thyroid carcinoma." (PMID 38321558, 2024). "BACH1 regulates heme homeostasis and effectively mediates oxidative stress, thus playing an essential role in inflammatory diseases and cancer." (PMID 38321558, 2024). "The following sections will elaborate on the roles of BACH1 in metabolism, invasion, metastasis, proliferation, and different cell death pathways of cancer cells." (PMID 38321558, 2024). "Taken together, BACH1 represses the innate and adaptive immune response in lung oncogenesis, thus playing a cancer-promoting role." (PMID 38321558, 2024). "The roles of the significantly increased expression of BACH1 in various immune cells are yet to be explored, while the BACH1-mediated complex regulatory network in diverse cancer types and immune cells also merits further investigation." (PMID 38321558, 2024). "The crosstalk between calcium and BACH1 sheds further light on the regulation of cancer metastasis by calcium." (PMID 36453019, 2023). "Several studies have established that BACH1 promotes progression of various types of cancers via multiple mechanisms, as reviewed." (PMID 36774506, 2023). "This analysis further strengthens the pan-cancer trends that we noticed earlier in terms of the antagonistic association of RKIP and BACH1 with multiple axes of phenotypic plasticity." (PMID 37963558, 2023). "OXPHOS ssGSEA scores correlated positively with RKIP in 88.57% (31 out of 35) of the cancer types, while BACH1 correlated negatively in 91.14% (32 out of 35) of the cancer types." (PMID 37963558, 2023). "BACH transcription factors, especially BACH1, are involved in the proliferation, metastasis, angiogenesis, metabolism, and chemotherapy resistance of many cancers." (PMID 37228820, 2023). "Together, our systems-level analysis indicates that the emergent dynamics of underlying regulatory network enable the antagonistic patterns of RKIP and BACH1 with various axes of cancer cell plasticity, and with patient survival data." (PMID 37963558, 2023). "BACH1 regulates cancer proliferation by targeting IGF1R and PTK2 and affecting angiogenesis and cell cycle." (PMID 37228820, 2023). "CNC proteins, especially Bach1, are indispensable partners for small Mafs to influence the process of cancer metastasis and invasion." (PMID 36750911, 2023). "LncRNA SNHG8 decreases the level of miR-1270 to increase the expression of BACH1, thereby promoting cancer progression." (PMID 37228820, 2023). "BACH1 negatively regulates mitochondrial metabolism in cancer cells by affecting transcription of mitochondrial respiratory chain genes and glucose utilization in the citric acid cycle." (PMID 37228820, 2023). "It appears that BACH1 overexpression is a common feature in tumors with preferential lymphatic metastasis based on the pan-cancer analysis of TCGA data." (PMID 36670112, 2023). "The master regulatory role of Bach1 in cancer metastasis has been well discussed in many excellent reviews." (PMID 36750911, 2023). "On the other hand, the KS-Mes scores were negatively correlated with RKIP levels in 57.14% (20 out of 35) cancer types but positively correlated with BACH1 expression in 88.57% (31 out of 35) of cases." (PMID 37963558, 2023). "Further, RKIP showed a negative correlation with KS EMT score in 57.14% (20 out of 35) of cancers but BACH1 showed a positive correlation with it in 77.14% (27 out of 35) of cases." (PMID 37963558, 2023).
cancer (continued). "Heterodimers of small Mafs and Nrf2 stimulate cancer metastasis by inducing HO-1, the enzyme catabolizing heme, leading to elevated antioxidants and Bach1 stabilization." (PMID 36750911, 2023). "BACH1 is dynamically expressed in cancer development from the early lesions to invasive stages and are more highly expressed in cancer tissues than in normal tissues." (PMID 37228820, 2023). "Consistently, RPMS and BPMS ssGSEA scores correlated positively with one another in a pan-cancer manner, thus endorsing the pro-metastatic role of BACH1 and an anti-metastatic role of RKIP." (PMID 37963558, 2023). "Similar trends were observed with FAO, with RKIP correlating positively and BACH1 correlating negatively with the corresponding ssGSEA scores in 31 out of 35 cancer types." (PMID 37963558, 2023). "RKIP and BACH1 were found to be negatively correlated with each other in 31 out of 35 (88.57%) cancer types." (PMID 37963558, 2023). "BTB and CNC homology 1 (BACH1) is classified as a transcription factor, which is reported to be an oncogene in cancer." (PMID 35651942, 2022). "The result presented the potential of BACH1 to be a reliable biomarker for the prognosis of pan-cancer patients and a new target for cancer treatment." (PMID 35651942, 2022). "In this paper, by systematically analyzing the data from TCGA database, we present the role of BACH1 as a novel cancer therapeutic target and highlight the latent utility of BACH1 in cancer targeting therapy." (PMID 35651942, 2022). "In HCC, BACH1 functions as a cancer-promoting gene, facilitating cell proliferation, migration, and invasion." (PMID 35154476, 2022). "Through systematic analysis of BACH1 expression and function in different cancer types, we demonstrated the profound impact of BACH1 on tumor physiology and overall survival." (PMID 35651942, 2022). "We found that the expression of BACH1 in most cancer types is positively related to the level of TILs infiltration." (PMID 35651942, 2022). "The orchestration of a complex cell signal network that affects the proliferation and invasion of cancer destines BACH1 to be a promising predictor of the prognosis of NSCLC and a new potential cancer target." (PMID 35035660, 2022). "Not only that, multiple pieces of research pointed out that BACH1 has been a potential therapeutic target for most cancers." (PMID 35067159, 2022). "Until now, our research is the first to thoroughly elucidate the correlation between BACH1 expression and OS or physiology in cancer patients at pan-cancer level." (PMID 35651942, 2022). "It is demonstrated that BACH1 is highly expressed in multiple cancers, and involved in metabolism and immune pathways by regulating its target genes." (PMID 35651942, 2022). "Hemin treatment induced the ubiquitin-dependent degradation of BACH1 protein, reprogrammed cancer metabolism, and generated cancer vulnerability against mitochondrial oxidative phosphorylation inhibitors." (PMID 35406740, 2022). "This study highlights the essential role of BACH1 through in-depth analysis of the relationship between BACH1 and OS, cancer metabolism, TMB and immune cell infiltration." (PMID 35651942, 2022). "The transcription factor BTB and CNC homology 1 (BACH1), is a member of Cap’n’Collar and leucine zipper family that involves in the progression of several cancers, such as prostate cancer and ovarian cancer." (PMID 34351577, 2022). "We found that BACH1 is highly expressed in abundant cancers and correlated with the poor prognosis of most cancers." (PMID 35651942, 2022). "Our data indicates that targeting BACH1 generates metabolic vulnerability and increases sensitivity to lactate transporter inhibition, suggesting a potential novel combination therapy for cancer patients with TNBC." (PMID 35406740, 2022). "BACH1 expression is known to be regulated at post-transcriptional or translational levels in cancer cells." (PMID 33809182, 2021).
cancer (continued). "Taken together, these observations indicate that cancer cells acquire metastatic potential when the activity of BACH1 is increased." (PMID 34339740, 2021). "In BRAF (V600E) mutant colon and skin cancer, BACH1 forms a complex with MAFG to mediate the function of DNA methyltransferase (DNMT3B) for hypermethylation of their target promoters to induce cancer progression." (PMID 33809182, 2021). "By synthesizing these observations, we propose a “two-faced BACH1 model”, which accounts for the dynamic switching between metastasis and stress resistance along with cancer progression." (PMID 34339740, 2021). "BACH1 can restrict dependency on oxidative phosphorylation and promote aerobic glycolysis in cancer cells, a phenomenon known as the Warburg effect." (PMID 34339740, 2021). "The results of in vitro assays also support the involvement of BACH1 in the metastatic properties of cancer cells." (PMID 34339740, 2021). "The two-faced BACH1 model posits that both the increase and the decrease of BACH1 activity are involved in the progression of cancers but with distinct expression of cancer cell properties." (PMID 34339740, 2021). "BACH1 promotes cancer metastasis and RKIP suppresses cancer metastasis, showing two molecules with opposite functions suppress each other." (PMID 33809182, 2021). "In support of preclinical studies, bioinformatic analyses of patient tumor expression data from The Cancer Genome Atlas (TCGA) highlighted mitochondrial OXPHOS regulated by BACH1 in numerous cancer types." (PMID 33809182, 2021). "The growing list of BACH1 target genes in cancer cells reveals that BACH1 promotes metastasis by regulating various sets of genes beyond iron metabolism." (PMID 34339740, 2021). "While many of the established target genes of BACH1 in normal cells are related to metabolism of iron, heme, and ROS, its target genes in cancer cells appear more diverse than those in normal cells, without any apparent direct connection to iron or heme." (PMID 34339740, 2021). "If we can inhibit the degradation of BACH1 in cancer cells upon induction of ferroptosis, the efficacy of anticancer therapies involving ferroptosis, not only cytotoxic drugs but also immune checkpoint therapies, will be further enhanced." (PMID 34339740, 2021). "When active, BACH1 not only induces the expression of genes for cancer progression but also represses the expression of a cohort of stress-responsive genes." (PMID 34339740, 2021). "Although these models provide compelling evidence supporting the importance of BACH1, additional genetic models such as oncogene-driven cancer development in mice need to be tested." (PMID 34339740, 2021). "Recent studies identified novel functional roles of BACH1 in the regulation of metabolic pathways in cancer cells." (PMID 33809182, 2021). "The flexible metabolic phenotypes of cancer that are altered by BACH1 suggest BACH1 as a useful target for cancer vulnerability against mitochondrial inhibitors." (PMID 33809182, 2021). "The flexibly altered cancer metabolism by BACH1 inhibition also plays as a primary metabolic pathway in cancer, thereby generating metabolic liability when this primary metabolism is blocked." (PMID 33809182, 2021). "Investigations on various types of human cancers have established that BACH1 promotes cancer progression via multiple mechanisms." (PMID 34339740, 2021). "Mechanistically, some of the studies revealed that BACH1 functions as a master transcriptional regulator of cancer progression and metastasis." (PMID 33932125, 2021). "BACH1-enriched cancer cells showed promoted metastatic properties such as migration, invasion, intravasation and metastasis of cancer cells both in vivo and in vitro." (PMID 33809182, 2021). "Increasing evidence indicated that BACH1 promotes metastasis in various human cancers; however, the functional role and mechanism of action of BACH1 in ESCC have not been elucidated." (PMID 33932125, 2021).
cancer (continued). "Further understanding of the BACH1 GRN in cancer cells will allow a rational development of therapeutic strategies." (PMID 34339740, 2021). "Nuclear factor κB (NF-κB) and Bach1 also play a key role in the occurrence and development of cancer 92, and is considered to be a target for the cancer therapy." (PMID 34239353, 2021). "A new transcription factor, named BTB and CNC homology 1 (BACH1), has recently emerged as a central actor connecting redox balance to cancer metabolism reprogramming." (PMID 33499022, 2021). "NAD+/NADH ratios are important factors in determining metformin responses of cancer cells and were also altered by BACH1." (PMID 33809182, 2021). "Metabolomics, microarray and deep-sequencing approaches revealed that a metastasis promoting transcriptional factor, BACH1, participates in metabolic reprogramming of cancer cells." (PMID 33809182, 2021). "This review highlights recent advances in an understanding of the newly discovered essential role of BACH1 on cancer metabolism and its potential as a therapeutic target for cancer therapy." (PMID 33809182, 2021). "Further studies will be needed to determine if BACH1 promotes angiogenesis in cancer tissues, perhaps as an extension of the regulatory role played by BACH1 and/or BACH2 in developmental angiogenesis." (PMID 34339740, 2021). "We discuss here the possibility that BACH1-mediated promotion of cancer also brings increased sensitivity to iron-dependent cell death (ferroptosis) through crosstalk of BACH1 target genes, imposing programmed vulnerability upon cancer cells." (PMID 34339740, 2021). "Bach1 is a transcriptional regulator that controls expression of several groups of genes important for metabolism and metastasis of cancer cells." (PMID 34807950, 2021). "Particularly, targeting BACH1 using hemin when combined with a metabolic inhibitor, metformin, projected promising therapeutic intervention as a novel combination drug for cancer patients." (PMID 33809182, 2021). "To understand how BACH1 shuts off its interactions with corepressors to transactivate gene expression, we need first to quantify those protein molecules in cancer cells." (PMID 34339740, 2021). "We will next explore BACH1's links to cancer metastasis, which will help demonstrate how these roles intersect with cancer biology." (PMID 34339740, 2021). "In this regard, transforming growth factor-β, a critical growth factor regulating the EMT process and cancer niche signaling, is interesting, as it induces the expression of BACH1 and MAFK." (PMID 34339740, 2021). "We recently reported that DHA induces HO-1 gene transcription in human cancer cells by augmenting the degradation of Bach1 protein, which functions as a negative regulator of HO-1." (PMID 30367621, 2018). "Pretreatment of cancer cells with Sorafenib significantly attenuated DHA-induced degradation of Bach1 protein." (PMID 30367621, 2018). "Interestingly, biallelic inactivation of BACH1 was recently observed in patients with Fanconi Anemia (FA), a recessive chromosomal instability disorder characterized by developmental abnormalities, growth retardation, bone marrow failure, and early predisposition to cancer." (PMID 16430786, 2006). "By activating ferroptosis through diverse mechanisms, BACH1 might offer a potential treatment strategy for cancers." (PMID 39887888, 2025). "Oxygen tension or diffused oxygen concentration in the tumor microenvironment might directly or indirectly affect BACH1 protein expression levels to promote cancer metastasis." (PMID 40710214, 2025). "Finally, the significant correlation between basal BACH1 levels and signature genes expression across multiple cancer types supports the role of BACH1 as a key regulator of this gene set, despite the potential influence of other transcription factors." (PMID 40716152, 2025). "Inhibit BACH1 expression increasing autophagy and apoptosis of cancer cells." (PMID 41465470, 2025).
cancer (continued). "Moreover, antioxidants promote cancer metastasis by lowering the free heme levels and stabilizing BACH1." (PMID 40563308, 2025). "BACH1 expression in immune cells affects tumorigenesis and cancer cells produce high ROS levels." (PMID 38321558, 2024). "In addition, docosahexaenoic acid (DHA) -induced lipid peroxidation leads to the degradation of BACH1, promoting the expression of the HO-1 gene in human cancer cells." (PMID 38321558, 2024). "As a transcription factor, BACH1 has a well-established role in promoting cancer invasiveness." (PMID 38895309, 2024). "In addition, BACH1 is regulated by other signals and thus also indirectly influences glycolysis in cancer cells." (PMID 38321558, 2024). "Notably, BACH1 is highly expressed in almost all cancer types and plays a crucial role in the key processes of tumorigenesis including cancer metabolism, metastasis, proliferation, and drug resistance." (PMID 38321558, 2024). "At the same time, BACH1 upregulates the malignant features of cancer stem cells (CSCs)." (PMID 38321558, 2024). "At the same time, some previous studies revealed its cancer-suppressing effect, and BACH1 may negatively affect cancer cell survival by mediating protein homeostasis." (PMID 38321558, 2024). "BACH1 plays an essential role in regulating cancer cell proliferation." (PMID 38321558, 2024). "Expression of BACH1 is related to tumor-infiltrating immune cells in different cancer types, and it is positively correlated with the level of tumor-infiltrating lymphocytes (TILs) in most cancer types according to the TIMER algorithm." (PMID 38321558, 2024). "BACH1 has different functions in the regulation of apoptosis in the progression of cancer." (PMID 38321558, 2024). "However, the current research status provides little information on how BACH1 is post-translationally modified and dysregulated in cancer." (PMID 38321558, 2024). "Thus, the balance between NRF2 and BACH1 activity determines the cellular response to oxidative stress in cancer." (PMID 39090114, 2024). "For example, inhibiting metastasis activator BACH1 is proposed to decrease cancer metastases." (PMID 37231268, 2023). "Further, differential roles played by Bach1 in cancer cells and hepatocytes may be influenced by the cell types, the external environment, and the metabolic state." (PMID 38129407, 2023). "These ‘teams’ enable the BACH1-high cells to display a hybrid E/M and/or mesenchymal state exhibiting a stem-like behaviour, as well as opposite trends in terms of association of RKIP and BACH1 with patient survival across cancer types." (PMID 37963558, 2023). "BACH1 is a novel therapeutic target for regulating cancer progression." (PMID 37444447, 2023). "BACH1′s role in cancer progression is vital and includes regulation of iron homeostasis and related reactions, regulation of the oxidative stress response, enhancement of cancer cell metastasis, and promotion of aerobic glycolysis and EMT." (PMID 37444447, 2023). "The BACH1 accumulation led to the start‐up of the metastasis progression of cancer cells." (PMID 36453019, 2023). "BACH1 has been shown to promote cancer metastasis by promoting EMT." (PMID 37228820, 2023). "We found RKIP and BACH1 to be anti-correlated with each other in most cancer types." (PMID 37963558, 2023). "Pan-cancer observations consistently indicate that low RKIP and high BACH1 expression profile is linked with a worse survival outcome as compared to a high RKIP and low BACH1 one." (PMID 37963558, 2023). "ROS production is promoted by BACH1 in cancer cells but inhibited by BACH1 in macrophages." (PMID 37228820, 2023).